MTA1 (metastasis associated 1)
Diseases named in the same sentence as MTA1 in open-access papers (continued):
Sharing a sentence is not in itself a finding about the gene and the disease.
cancer (continued). "Moreover, HSF1 seems to participate to the metastatic potential of the cancer cell through cooperation with different metastatic related genes, such as the prometastatic co-repressor gene MTA1." (PMID 24212658, 2011). "Expression of MTA1 has been correlated with metastatic potential in two types of carcinomas." (PMID 22030022, 2011). "Furthermore, a similar distribution and expression level of MTA-1 was observed in murine tissues and cancer cell lines." (PMID 18949081, 2008). "Furthermore, the ZEB1/NuRD(MTA1) complex was confirmed to regulate glycolysis and promote invasiveness of cancer cells, suggesting that the NuRD complex plays a role in glycolysis and cancer progression in CRC." (PMID 39193340, 2024). "Besides strong correlation between MTA1 upregulation and cancer, growing evidence strongly suggests that MTA1 could regulate divergent cell pathways by modifying status of crucial target genes under both pathological and physiological statuses." (PMID 36786127, 2023). "Besides strong correlation between MTA1 upregulation and cancer, growing evidence strongly suggests that MTA1 could regulate divergent cell pathways by altering the status of key target genes in pathological and physiological states." (PMID 36786127, 2023). "Moreover, MTA1 is gradually perceived to be a new target candidate for cancer drug treatment." (PMID 34502289, 2021). "Moreover, MTA1 could mediate the migration and invasion of cancers by regulating the phosphorylation of various intracellular proteins involved in signaling pathways, such as AKT, hypoxia, and hedgehog signaling." (PMID 33059651, 2020). "Therefore, MTA1 has been considered an ideal target for cancer immunotherapy." (PMID 30596107, 2018). "This may indicate that MTA1 is critical in the life activity of cancer cells." (PMID 24396455, 2014). "Consequently, PROX1 and MTA1 are regarded as useful biomarkers for the diagnosis, prognosis, and treatment of malignancies in humans; nevertheless, additional research is required to thoroughly evaluate their function in cancer therapy and their potential clinical application." (PMID 40660330, 2025). "MTA1 modulates the expression of genes related to epithelial-mesenchymal transition (EMT), a process by which cancer cells acquire a more invasive and migratory phenotype." (PMID 39355129, 2024). "The colocalization of MTA1 and ATP5A was also verified in mouse derived cancer cell line CT26 and other cancer cell lines, including MCF7, MDA‐MB‐231, and HeLa cells." (PMID 37442756, 2023). "Overall, this study revealed that the interaction between mitochondrial MTA1 and ATP5A drives cancer liver metastasis by increasing OXOPHOS and ATP production." (PMID 37442756, 2023). "Thus, MTA1 may be a potential biomarker and therapeutic target for everolimus‐resistant cancer." (PMID 37442756, 2023). "We found that RUNX2, MTA1, or CUL4B depletion inhibited the proliferation of cancer cells, whereas RUNX2, MTA1, or CUL4B overexpression significantly promoted proliferation." (PMID 35534547, 2022). "The MTA family shares many similar characteristics, but each of these three members, MTA1, MTA2, and MTA3, exhibit significant differences in cancer progression and metastasis." (PMID 35534547, 2022). "Additional studies provided evidence that miR-30-5p and miR-33a target MTA1 and METTL3, respectively, hence contributing to attenuated anchorage-independent growth of cancer cells." (PMID 33435156, 2021). "Most of the current understanding of the MTA1 functions in HCC and other cancer types is derived from in vitro studies." (PMID 34502289, 2021).
cancer (continued). "Based on the roles of PRMT5, Snail, and MTA1 in EMT and cancer progression, we then further identified the functional coordination of the Snail/PRMT5/NuRD(MTA1) complex on target promoters using transwell assays." (PMID 33953349, 2021). "VEGF, Ki67, Bax, Bcl-2, MTA1, and MMP2 expression in cancer tissues was consistent with those in cancer cells, as revealed by immunohistochemical staining." (PMID 34900992, 2021). "MTA1 accesses nucleosomes and represses DNA-dependent transcription by coupling with HDAC through its ELM2-SANT domains, in favor of oncogenesis and cancer progression." (PMID 32901005, 2020). "We found that MTA1 staining was significantly increased in CIN and cancer tissues compared to normal cervical tissues." (PMID 31281798, 2019). "We found that four peptides of MTA1, P22, P57, P109, and P129, induced CD8+ T cells to secrete IFN-γ and lyse cancer cells both in vitro and in vivo." (PMID 30596107, 2018). "Further this study highlights the clinical significance of MTA1, DNMT3a and IGFBP3 in determining an overall poor prognosis of cancer patients." (PMID 28393842, 2017). "Compared with normal lung tissues, MTA1 expression was elevated in NSCLC patient tissues and was correlated with American Joint Committee on Cancer stage, T stage, lymphatic metastasis, and patient overall survival." (PMID 28418915, 2017). "MTA1 is overexpressed in a variety of human cancers, including NSCLC, providing a new molecular target for anti-cancer therapeutics." (PMID 28418915, 2017). "In the current study, silencing of MTA1 reversed the cancerous behaviors of LSCC, extending the therapeutic value of MTA1 in cancer treatment." (PMID 24396455, 2014). "Therefore, MTA1 may be one of the significant molecules in cancer progression." (PMID 25009653, 2014). "MTA1 is correlated with cigarette smoking in NSCLC, indicating its importance in the smoking-related progression of this type of cancer." (PMID 24396455, 2014). "To further determine the role for MTA1 in cancer differentiation, we utilized expression profile chip analysis to compare the genome features between HCT116 control and MTA1-overexpressing HCT116-M3 cells." (PMID 24970816, 2014). "While MTA1 is a “new” molecule in canine UC, the inducible COX2 inflammatory and oncogenic pathway that participates in cancer cell proliferation, migration, survival, stimulation of angiogenesis and promotion of drug resistance has already been recognized in canine and human invasive UC." (PMID 40351767, 2025). "On the other hand, low-grade carcinomas mainly demonstrated low (9 cases, 75%), and negative (2 cases, 16.7%) MTA1 expression." (PMID 40660330, 2025). "Regarding the p16 status, used as a surrogate parameter for infection with human papilloma virus, the statistical analysis showed that the percentage of cells expressing MTA1 was higher in carcinomas with negative p16 status (p = 0.014)." (PMID 36689059, 2023). "Here, we confirmed that RUNX2 could recruit the NuRD(MTA1)/CRL4B complex to induce cell proliferation, invasion, tumorigenesis, and bone metastasis, as well as cancer stemness." (PMID 35534547, 2022). "To check if MTA1 plays any role in cancer cell migration, we transfected the cells with either siRNA targeting MTA1 or negative control siRNA and performed wound healing assays." (PMID 31281798, 2019). "Opposed to effects on CTSB and as expected based on our previous observations, MTA1 negatively regulates E‐cad expression in primary tumor, a hallmark of EMT associated with metastasis, indicating the impact of MTA1 in the process of EMT and cancer cell ability to migrate to distant sites." (PMID 30027683, 2018). "Results from our MTA1 ChIP‐Seq analysis along with VEGF‐c and IL‐1β10, identified HIF‐1α as a novel transcriptional target of MTA1 in PCa, emphasizing the importance of MTA1 in the promotion of cancer angiogenesis and metastasis." (PMID 29024573, 2017).
cancer (continued). "Due to the positive feedback loop between MTA1 and p-AKT, blocking both MTA1 and p-AKT may represent a novel therapeutic strategy for cancer treatment." (PMID 28418915, 2017). "Interesting, in addition to MTA1, IGFBP3 is also overexpressed in many other human cancers." (PMID 28393842, 2017). "Finally, among the few genes downregulated in EXO/miR-222 we detected MTA1 and MTA2, nuclear receptor coregulators overexpressed in human cancers, but reported to play a dual role being either corepressors or coactivators." (PMID 26912358, 2016). "The clinical efficiency of targeting MTA1 biomolecules has not yet been proven, but several studies have suggested MTA1 protein or gene as a molecular target for cancer therapy." (PMID 26878004, 2016). "An important question that arises from this study is why elevated levels of YB-1 and MTA1 are most predictive for PSA recurrence in PIN lesions as opposed to cancer lesions?" (PMID 25797255, 2015). "Lenti-shMTA1 infection inhibited cell migration, and the Lenti-MTA1 infection promoted migration capacity of cancer cells when compared with negative control cells (p < 0.05)." (PMID 26698569, 2015). "Since MTA1 is a histone deacetylase (HDAC)-interacting protein that modulates the epigenetic status of its target genes, it is expected to widely influence the expression pattern of the cancer-related gene spectrum." (PMID 24396455, 2014). "Of the molecules involved in cancer metastasis, MTA1 is an important one but certainly not the only." (PMID 25332145, 2014). "In contrast to MTA1 and MTA2, which are usually upregulated in cancer, MTA3 is downregulated." (PMID 23671646, 2013). "The mechanisms leading to the upregulation of MTA1 protein expression in human cancers are not known." (PMID 22537306, 2012). "Our results indicate that the prognostic value of MTA1 is most significant in early-stage NPC patients, especially those with stage II disease, and similar findings have also been reported in other types of cancer." (PMID 22537306, 2012). "Low-grade carcinomas mainly present low and negative MTA1 expression." (PMID 40660330, 2025). "Moreover, both MTA1 and METTL3 are realized to accelerate cancer metastasis." (PMID 33435156, 2021). "We speculate that MTA1-AKT interaction mechanisms differ between normal and carcinoma cells." (PMID 28418915, 2017). "Therefore, it is no surprise that MTA1 overexpression correlates well with cancer metastasis and is often an indicator of poor prognosis, no matter it has a role in metastasis or not." (PMID 25332145, 2014). "We may have a glimpse of MTA1’s role in carcinogenesis and cancer metastasis, not from a mechanistic but a biological point of view." (PMID 25332145, 2014). "Although both MTA1 and MTA2 are among the most upregulated in human cancers, their functions do not always overlap." (PMID 41159000, 2025).
cancer (continued). "However, we do not explore the regulation process between cancer stem cells and EMT by MTA1, and this will be explored in our following works." (PMID 33282725, 2020).
infection (8 papers, 2012 to 2024). The state of being infected such as from the introduction of a foreign agent such as serum, vaccine, antigenic substance or organism. "Recently, in the rice blast fungus Magnaporthe oryzae, MT-A70 domain protein 1 (MTA1, orthologous to human METTL4) was shown to play an important role in appressorium formation during infection process via regulation of autophagy process." (PMID 38085094, 2024). "In the rice blast fungus M. oryzae, a knockout strain lacking MTA1 showed a defect in appressorium formation during the infection process on the epidermal cells of rice." (PMID 38085094, 2024). "For example, Sh3gl3 (or endophilin A3) has been observed binding with a number of proteins, including Mta1, and may be involved in endocytosis, although the role this might play in infection is not clear." (PMID 22384400, 2012).
MTA1 also shares sentences with these, for which no sentence is quoted: adenocarcinoma (4 papers); esophageal squamous cell carcinoma (3); metastasis (2); prostate (2); renal carcinoma (2); small cell lung carcinoma (2); bacterial infections (1); benign tumors (1); bladder urothelial carcinoma (1); bone metastasis (1); chronic cervicitis (1); chronic nasopharyngitis (1); craniosynostosis (1); dysplasia (1); endometrial adenocarcinomas (1); epilepsy (1); Ewing sarcoma (1); gastric adenocarcinoma (1); gastrointestinal disease (1); genetic disorders (1); glioblastoma multiforme (1); head and neck tumour (1); infertile (1); inflammatory bowel disease (1); insomnia (1); invasive breast carcinoma (1); large cell carcinoma (1); laryngeal carcinoma (1); lung tumor (1); malignant mesothelioma (1).
A further 7 diseases each share a sentence with MTA1 in 1 paper.